HMGB1 (high mobility group box 1)
Diseases named in the same sentence as HMGB1 in open-access papers (continued):
Sharing a sentence is not in itself a finding about the gene and the disease.
Sepsis (continued). "High mobility group box 1 (HMGB1) protein is an important mediator of inflammation implicated in sepsis pathophysiology." (PMID 23506269, 2013). "High-mobility group box 1 (Hmgb1) is an evolutionarily conserved, chromatin-binding protein that has been implicated in several disease states including sepsis, arthritis, ischemia-reperfusion injury, and cancer." (PMID 24453427, 2013). "With respect to acute inflammation, HMGB1 has been demonstrated to be of pathogenic relevance in sepsis, pneumonia, and endotoxemia." (PMID 23351605, 2013). "Although its safety and efficacy are widely accepted, the effect of GL on HMGB1 expression in sepsis or endotoxemia as well as the underlying molecular mechanism has not been reported up to now." (PMID 23497622, 2013). "Deregulation of HMGB1 has been shown to be associated with several inflammation associated diseases such as atherosclerosis, arthritis, and sepsis." (PMID 23766911, 2013). "Recent data demonstrated that levels of HMGB1 increased significantly in plasma after extensive burn injury, which was associated with the development of sepsis and fatal outcome of major burns." (PMID 23209806, 2012). "In this regard, TNF-α and HMGB1 have been intimately linked to the pathology of several inflammatory diseases, such as sepsis, rheumatoid arthritis and Crohn's disease." (PMID 21887276, 2011). "HMGB1 has been implicated in the pathogenesis of a number of diseases associated with inflammation and tissue injury, including sepsis." (PMID 20565784, 2010). "Taken together, previous studies and our results indicate different kinetics for the release of HMGB1 during the two major causes of shock: sepsis and hemorrhage." (PMID 19887013, 2009). "Gram-negativeand Gram-positive bacteria are able to cause sepsis, but little is known aboutthe HMGB1 inducing ability of mycobacteria." (PMID 18288272, 2007). "Targeting the HMGB1-sRAGE axis may represent a promising therapeutic strategy in sepsis-associated renal injury." (PMID 42075493, 2026). "Elevated PKM2 expression activates the transcription of HIF-1α and promotes the release of high mobility group box 1 (HMGB1) from activated macrophages, thereby amplifying sterile inflammation, particularly in sepsis-associated AKI, and enhancing TEC susceptibility to OS." (PMID 40843128, 2025). "As a significant mediator of both acute and chronic inflammation, HMGB1 is implicated in the onset and progression of numerous conditions, including systemic lupus erythematosus, myositis, sepsis, trauma, respiratory disorders, myocardial infarction, atherosclerosis, cancer and cerebral diseases." (PMID 39963819, 2025). "In murine polymicrobial sepsis models, HMGB1 levels usually peak late, associating with death." (PMID 40429966, 2025). "In addition, a previous study demonstrated the association of HMGB1 with sepsis in serum and cells of AOSC patients, with HMGB1 levels progressively decreasing with treatment." (PMID 40054422, 2025). "Notably, the HMGB1/NLRP3 axis is also implicated in cognitive dysfunction associated with sepsis, diabetes, and Alzheimer’s disease." (PMID 40688353, 2025). "Additionally, miR-22 mitigates sepsis-associated AKI via downregulation of the HMGB1/TLR4/NF-κB pathway, while miR-129-5p attenuates LPS-induced AKI by targeting the HMGB1/TLR/NF-κB axis." (PMID 40727103, 2025). "Additionally, postoperative adverse outcomes based on subgroups of intraoperative HMGB1 levels suggested that biliary pancreatitis, sepsis, and death were associated with higher HMGB1 levels in bile during surgery." (PMID 40054422, 2025). "Furthermore, the effects of downregulated HMGB1 on ferroptosis and oxidative stress in sepsis‐induced ALI were explored, and the underlying molecular mechanisms were investigated." (PMID 38837857, 2024). "Despite these findings, the precise mechanism underlying the regulatory effects of HMGB1 on ferroptosis and oxidative stress in sepsis‐induced ALI remains unclear." (PMID 38837857, 2024).
Sepsis (continued). "Identified in 1999 as a late-stage mediator of sepsis, HMGB1 acts as a damage-associated molecular pattern (DAMP), prolonging inflammation by activating macrophages via Toll-like receptor 4 (TLR4) and the receptor for Advanced Glycation Endproduct (RAGE) pathways." (PMID 39201697, 2024). "Given HMGB1's role in the coagulopathy associated with sepsis, it may serve as a potential therapeutic target for anticoagulant treatment, with interventions aimed at HMGB1 potentially improving the coagulation function in septic patients." (PMID 39445002, 2024). "Clinical observations link lactate concentrations and HMGB1 levels in sepsis patients, though causality remains unclear." (PMID 38812044, 2024). "Importantly, TN specifically binds high mobility group box1 (HMGB1), enhancing the cellular uptake of HMGB1 that can cause hyperinflammation and immunosuppression in lethal sepsis." (PMID 38187250, 2024). "Patients with sepsis have high levels of HMGB1, which have been associated with poor outcomes." (PMID 38474222, 2024). "PKM2 is an important regulator of HMGB1 secretion, and this danger/damage-associated molecular pattern, secreted together with TNFα, has been associated with inflammatory macrophages and can cause lethal sepsis." (PMID 37475858, 2023). "Furthermore, circTLK1 promotes inflammation and oxidative stress via the miR-106a-5p/HMGB1 axis in sepsis-associated acute kidney injury, and hsa_circ_0003091 mediates sepsis-induced lung injury by reducing miR-149." (PMID 36625877, 2023). "AKI induced by renal ischemia-reperfusion 19, sepsis 25, and nephrotoxins including contrast agents 41 all causes the release of HMGB1, which may activate downstream signaling pathways for the recruitment and activation of inflammatory cells." (PMID 37284446, 2023). "Although there are limited data available about the role of HMGB1 in neuroinflammation following sepsis, it has been implicated in other neurologic disorders with neuroinflammatory features such as traumatic brain injury (TBI) and peri-operative neurocognitive disorders (PNDs)." (PMID 37048161, 2023). "In clinical settings, the plasma levels of HMGB-1 were associated with the severity and mortality attributed to sepsis and correlated with RIPK3 (receptor interacting protein kinase 3) and MLKL (mixed lineage kinase domain-like protein), suggesting an association of HMGB-1 with necroptosis." (PMID 36005726, 2022). "In addition, we examined the effect of CD19hiFcγRIIbhi B cells with the HMGB1 (C106A) mutation on the progression of sepsis." (PMID 35983056, 2022). "HMGB-1 is associated with sepsis, malignancy, and immune disease, including ALI/ARDS." (PMID 35204430, 2022). "It was also involved in sepsis-associated liver injury via induction of the intracellular translocation of the high-mobility group box 1 (HMGB1), which, in turn, was associated with a direct interaction of SphK1 and the calcium/calmodulin protein kinase II-δ (CaMKII-δ)." (PMID 36361636, 2022). "In particular, HMGB1 is associated with many disease, such as sepsis, influenza virus, and cancer, which could interact with the extracellular region of RAGE and mediate the inflammatory response." (PMID 35328729, 2022). "Conversely, the release of HMGB1 from hepatocytes increases the risk of liver damage during sepsis." (PMID 35222035, 2022). "Lastly, the DAMPs we note increased, were previously shown to trigger the cytokine storm (e.g., HMGB1), cause thrombosis (e.g., extracellular dsDNA, histone-DNA complexes) and result in a clinical picture of severe sepsis." (PMID 35502320, 2022). "In humans with sepsis, the presence of HMGB-1 has been associated with poor outcomes." (PMID 33718468, 2021). "Our findings suggest that HMGB1 has the potential as a diagnostic marker for sepsis." (PMID 34743181, 2021). "Besides, high serum levels of HMGB1 are associated with death, and tissue damage in sepsis patients." (PMID 34784841, 2021).
Sepsis (continued). "Importantly, HMGB1 has been implicated in the pathogenesis of numerous inflammatory disorders including sepsis, lung conditions, autoimmune diseases, acute liver injury, cardiac injury, encephalopathy and other inflammation-driven conditions." (PMID 33925132, 2021). "However, the roles of HMGB1 released by damaged podocytes in sepsis-associated AKI remain largely undetermined." (PMID 34616232, 2021). "Plasma levels of HMGB1 were associated with the severity and mortality attributed to sepsis." (PMID 33947887, 2021). "Although the accumulating literature has reported that HMGB1 is closely related to cognitive dysfunction caused by a variety of reasons, such as neurodegenerative diseases, surgery, and sepsis, the association between p-tau and HMGB1 in a delayed period post injury remains undefined." (PMID 34539383, 2021). "We have previously identified that increased expression of cerebral HMGB1 was one of the major causes of sepsis induced brain injury, as shown by abnormal structure of brain tissues, massive neuronal apoptosis, and cognitive impairment, and these effects were alleviated by administration of BoxA." (PMID 34512319, 2021). "Thence, further understanding of HMGB1-associated pathogenesis of sepsis may assist in development of promising treatment strategies." (PMID 33552058, 2020). "As an early mediator of inflammation, HMGB1 is implicated in a variety of inflammatory diseases, including sepsis, arthritis and pneumonia, thereby indicating that HMGB1 maybe be a promising therapeutic target for inflammatory diseases." (PMID 32595744, 2020). "Initially, HMGB1 was shown to cause a danger signal in acute inflammatory diseases such as sepsis." (PMID 32760399, 2020). "Since previous studies showed that the expression of HMGB1 and SphK1 is elevated in sepsis-associated liver damage, whether HMGB1 and SphK1 are related remains unknown." (PMID 33281190, 2020). "Administration of HMGB1 to mice can cause lethal organ damage similar to that seen in sepsis." (PMID 32197507, 2020). "We explored whether hepatocytes or Kupffer cells were the major cells secreting HMGB1 during sepsis-associated liver damage." (PMID 33281190, 2020). "However, little information is available on the association between SphK1 and HMGB1 translocation during sepsis-associated liver injury." (PMID 33281190, 2020). "However, we have only described the advantage of the antagonism of central HMGB1 in sepsis; the mechanism underlying the crosstalk between the brain and peripheral organs remains to be clarified." (PMID 30881224, 2019). "During sepsis, the systemic and local inflammatory responses are strongly driven by damage-associated molecular patterns (DAMPs), such as eCIRP and HMGB1, released by dying cells, as well as pathogen-associated molecular patterns (PAMPs), like endotoxin and peptidoglycan, released by bacteria." (PMID 31747882, 2019). "Therefore, an increased release of cerebral HMGB1 should be recognized and promptly addressed as it underlies the protective effects of the intact neuroendocrine immune network against sepsis." (PMID 30881224, 2019). "HMGB1 is associated with divergent clinical conditions such as sepsis." (PMID 30157804, 2018). "HMGB1 is a late mediator of sepsis-associated ALI and is associated with ALI prognosis." (PMID 29795561, 2018). "While anti-HMGB1 pAb therapy increased survival in simple endotoxaemia and CLP sepsis, it was unknown whether anti-HMGB1 could potentiate immunosuppression and increased susceptibility to secondary infection." (PMID 28724977, 2017). "Additional studies are needed to elucidate further whether and how these agents, and CLEN, protect from HMGB1-associated inflammatory disorders such as septicemia." (PMID 28929026, 2017). "In addition to inflammatory cytokines (TNF-α, IL-1 and so on), HMGB1 has recently been shown to mediate the lethal late phase of sepsis and caused coagulopathy." (PMID 27011792, 2016).
Sepsis (continued). "Furthermore, elevated levels of HMGB1 have been implicated in the pathogenesis of a broad range of acute and chronic inflammatory conditions in sepsis, cancer, systemic lupus erythematosus and rheumatoid arthritis." (PMID 25889374, 2015). "For example, high-mobility group protein Box 1 (HMGB1), a chromatin-associated nuclear protein, has been reported to play an important role in the pathophysiology of sepsis, and plasma levels of HMGB1 have been reported as a marker of the severity of sepsis." (PMID 26161427, 2015). "Expression of HMGB1 in the endothelium and smooth muscle cells could be another cause of hemodynamic perturbation even from an early phase of severe sepsis." (PMID 23532259, 2013). "Clinical studies have found that in patients with sepsis and after hemorrhage, the elevated level of high mobility group box-1(HMGB-1) in their circulation is highly associated with ALI, but the underlying mechanism remains unclear." (PMID 23691208, 2013). "One interesting point is that increases in the late-phase cytokine HMGB1 are tightly associated with increased mortality in animal models of sepsis, whereas the administration of neutralizing antibodies to HMGB1 protects animals from death in the LPS and CLP models." (PMID 24098466, 2013). "Since there is very little knowledge of the role of HMGB-1/RAGE in the clinical setting of CAP-associated sepsis, we decided to perform a pilot study to investigate of HMGB-1, RAGE and sRAGE levels in septic patients with CAP and identify if there is a correlation with severity assessment scores." (PMID 22264245, 2012). "Extensive burn injury could result in significantly increased HMGB1 levels, which appears to be associated with the development of sepsis and fatal outcome of major burn." (PMID 23209806, 2012). "In addition, high serum levels of HMGB1 in patients with sepsis or hemorrhagic shock have been reported to be associated with increased mortality and disease severity." (PMID 22883976, 2012). "We investigated whether systemic HMGB-1 levels are associated with indices of monocytic activation/function in patients with sepsis-induced immunosuppression." (PMID 20652004, 2010). "Furthermore, in a recent study of sepsis, severe cardiovascular failure was significantly associated with lower levels of serum HMGB1." (PMID 18577209, 2008). "Furthermore, the study found that HMGB1 levels were significantly elevated in patients who succumbed to sepsis, and that the administration of HMGB1 in murine models caused sepsis-like symptoms and death." (PMID 18577209, 2008). "In contrast, dys-regulated inflammatory response sustained by late-acting mediators (such as HMGB1) may be more pathogenic in lethal sepsis." (PMID 17987129, 2007). "Administration of HMGB1 to mice causes sepsis-like symptoms and death." (PMID 18288272, 2007). "However, combined treatment with LIPUS and IMI led to a significant reduction in HMGB1 levels, suggesting that this intervention could mitigate long‐term pathological consequences associated with sepsis induced by HMGB1." (PMID 41551210, 2026). "In addition, HMGB1 inhibition rescues muscle atrophy caused by cachexia; therefore, cuproptosis through HMGB1 may be a key factor in sepsis-induced SAW." (PMID 40182687, 2025). "This suggests that high levels of biliary HMGB1 intraoperatively are associated with the risk of sepsis in AOSC patients and that it's having a delayed decrease in postoperative bile may be associated with systemic inflammatory response syndrome due to septic infection." (PMID 40054422, 2025). "The assessment of DAMPs, such as HMGB1, netosis, nucleosomes, extracellular histones, and cell‐free DNA, in combination with other indicators might offer supplementary insights for diagnosis in sepsis‐associated DIC." (PMID 39822757, 2025).
Sepsis (continued). "HMGB1, a multifunctional and highly conserved nucleoprotein with two positively charged DNA-binding regions and a negatively charged tail, has been implicated in the pathogenesis of multiple critical illnesses, including sepsis, acute liver failure and severe trauma." (PMID 36855150, 2023). "Notably, SIRT1-mediated HMGB1 deacetylation mitigates acute kidney injury associated with sepsis." (PMID 38034869, 2023). "Our findings suggest that increased thrombin generation in sepsis or other inflammatory diseases associated with hypercoagulability could lead to overzealous production of platelet-derived HMGB1, previously shown to be associated with morbidity and mortality in human septic patients." (PMID 34235204, 2021). "In the combination therapy group, the sepsis-caused tissue injury was improved, as reflected by the tissue injury score, which was significantly reduced compared with the sham treatment group, consistent with the lowest level of HMGB1 found in the serum of the combination therapy group." (PMID 33603756, 2020). "However, which cells in the liver are predominantly secreting HMGB1 during sepsis-associated liver injury was unknown." (PMID 33281190, 2020). "Moreover HMGB1 is also associated with the process of sepsis-related immunosuppression." (PMID 33552058, 2020). "However, whether SphK1 may regulate HMGB1 translocation to mediate the development of sepsis-associated liver injury remains unknown." (PMID 33281190, 2020). "As elevated HMGB1 levels were associated with poor clinical outcomes and dysregulated inflammatory profiles in human patients, a passive immunotherapeutic approach to block HMGB1 was developed and assessed for impact on survival in three murine sepsis models of increasing complexity." (PMID 28724977, 2017). "Thus, targeting HMGB1 with antioxidant compounds may be an attractive therapeutic strategy for inflammation-associated diseases such as sepsis, ischemia and reperfusion injury, arthritis, diabetes, and cancer." (PMID 25904867, 2015). "The release of HMGB1 into the extracellular environment, where it can function as an endogenous danger signal or 'alarmin' to promote inflammation has been implicated in a number of diseases associated with tissue injury, including sepsis and acute lung injury." (PMID 20565784, 2010). "Background and Objectives: Sepsis-associated acute kidney injury (SA-AKI) is driven by exaggerated inflammation and oxidative stress, with the HMGB1-RAGE axis playing a pivotal role in amplifying tissue damage." (PMID 42075493, 2026). "High mobility group box 1 (HMGB1) acts as a crucial mediator during the late phase of sepsis, promoting the secretion of pro-inflammatory cytokines and thereby fueling inflammation and systemic complications." (PMID 42193989, 2026). "Examples include HMGB1 modification cascades in sepsis, macrophage state transitions in inflammation, fibroblast/angiogenic programs in wound environments, and DNA repair regulation in cancer drug resistance." (PMID 41732414, 2026). "This study aimed to investigate the renoprotective effects of papaverine in a feces-induced peritonitis (FIP) model of sepsis and to explore its impact on HMGB1-RAGE-mediated inflammatory and oxidative pathways." (PMID 42075493, 2026). "Yang Kun and his colleagues recently found that lactate was able to promote HMGB1 lactylation, leading to HMGB1 secretion and accumulation in sepsis mice." (PMID 40384873, 2025). "HMGB1 was initially reported to be released from lipopolysaccharide-stimulated macrophages and to function as a pro-inflammatory factor in sepsis." (PMID 40148311, 2025). "In septicemia, lactate triggers high mobility group box 1 (HMGB1) acetylation, which boosts endothelial permeability by inhibiting the deacetylase Sirtuin 1 via Hippo/YAP signaling, recruiting it to the nucleus of GPR81 in macrophages." (PMID 40066231, 2025). "MiR-103a-3p inhibits sepsis-induced liver injury by targeting high-mobility group box protein B1 (HMGB1)." (PMID 39067063, 2025).